OR4C13 (olfactory receptor family 4 subfamily C member 13)
Description:
Odorant receptor.
Tractability: Antibody: UniProt places it where antibodies can reach, with medium confidence; UniProt predicts a signal peptide or a membrane-spanning region; its Gene Ontology location is reachable by antibodies, with medium confidence.
Gene: Protein-coding gene on chromosome 11 (49,952,391 to 49,953,419, forward strand). Ensembl gene ENSG00000258817.
Subcellular location: Cell membrane
Pathways (Reactome):
Sensory Perception: Expression and translocation of olfactory receptors
Gene Ontology:
Molecular function: olfactory receptor activity; G protein-coupled receptor activity
Biological process: detection of chemical stimulus involved in sensory perception of smell; G protein-coupled receptor signaling pathway
Cellular component: plasma membrane; membrane
Genetic constraint (gnomAD): Loss-of-function variants: 23 observed, 14.4 expected, observed/expected ratio (o/e) 1.6, 90% interval 1.13 to 1.94. The synonymous counts are far from expectation, so gnomAD's model fits this gene poorly and the ratio says little. Missense variants: 490 observed, 358.96 expected, observed/expected ratio (o/e) 1.37, 90% interval 1.27 to 1.47. Synonymous variants: 168 observed, 131.09 expected, observed/expected ratio (o/e) 1.28, 90% interval 1.13 to 1.46.
Homologues: Orthologues: chimpanzee OR4C13 (96% identical), dog OR4C10 (82% identical), mouse Or4c10 (82% identical), dog OR4C10C (80% identical), rat Or4c10 (80% identical), rat Or4c10b (80% identical), mouse Or4c10b (79% identical), dog OR4C10F (78% identical), dog OR4C10E (78% identical), rat Or4c105 (77% identical), rat Olr655 (75% identical), mouse Or4c105 (74% identical), and 2 more. Paralogues in human: OR4C46 (84% identical), OR4C12 (66% identical), OR4C15 (62% identical), OR4A15 (61% identical), OR4C6 (61% identical), OR4C3 (60% identical), OR4C5 (60% identical), OR4A47 (60% identical), OR4C45 (59% identical), OR4A5 (57% identical), OR4B1 (56% identical), OR4C11 (55% identical), and 116 more.